STAT3 (signal transducer and activator of transcription 3)
Diseases named in the same sentence as STAT3 in open-access papers (continued):
Sharing a sentence is not in itself a finding about the gene and the disease.
breast cancer (continued). "Fibroblast-derived IL-6 stimulated growth and invasion of breast cancer cells in vitro through activation of STAT-3 signaling." (PMID 33809315, 2021). "Preclinical studies revealed that aberrant STAT3 expression mediates immunosuppression of tumor cells, while inhibition of STAT3 re-sensitizes therapy-resistance breast cancer cells to palbociclib treatment." (PMID 33477856, 2021). "CD44 also participates in the switch on different pathways (AKT, STAT3, β-catenin, among others) that activate, as a final event, different mesenchymal markers promoting invasion and metastasis in breast cancer cells." (PMID 33506060, 2021). "The overexpression of STAT3 and miR-106a-5p inhibitor reversed circRHOT1 depletion-inhibited proliferation and circRHOT1 depletion-enhanced apoptosis of breast cancer cells." (PMID 33686957, 2021). "We identified a novel function of circRHOT1 promoting malignant progression and inhibiting ferroptosis in breast cancer by regulating the miR-106a-5p/STAT3 axis." (PMID 33686957, 2021). "RSV exerts apoptosis in triple negative but also in ERα+ breast cancer cells by different molecular links such as Src tyrosine kinase activity as well as the signal transducer and activator of transcription 3 (STAT-3) phosphorylation in breast cancer cells." (PMID 34444715, 2021). "The inhibitor against the Y239/240-ShcA phosphorylation site has emerged as a novel therapeutic strategy to inhibit STAT3 activation and increase sensitivity breast cancer cells to immunotherapy." (PMID 33957948, 2021). "Together these data suggest that miR-106a-5p induces ferroptosis by targeting STAT3 in breast cancer cells." (PMID 33686957, 2021). "Stat3 regulates tyrosinase gene expression and transcript activity and thus plays a pivotal role in promoting breast cancer growth and metastasis." (PMID 33967793, 2021). "In another study, the frequency of the CD44+/CD24- population—marking breast cancer stem cells (CSCs)—was diminished, and the expression and activation of the pro-inflammatory IL-6/STAT3 pathway reduced after Sdc-1 siRNA knockdown." (PMID 34070901, 2021). "MDSCs also enrich breast cancer cells with stem-like properties by activating IL-6/STAT3 and NO/NOTCH signaling pathways with NO, leading to suppression of T cell activation." (PMID 34235155, 2021). "This contradicted previous studies which reported that STAT3 exacerbated breast cancer via various signaling 9,12." (PMID 34335938, 2021). "As previously reported, preclinical studies of small-molecule STAT3 inhibitor S3I-201 and C188 significantly retarded the breast cancer cell growth in xenografts." (PMID 33957948, 2021). "FABP4 supplementation increases tumor volume, tumor-initiating frequency and stemness markers, as shown in in vivo and in vitro studies on mammary tumors, depending on the IL-6/STAT3/ALDH1 signaling pathway." (PMID 34202411, 2021). "For example, in breast cancer, MSCs secreting IL-6 causes protection of MCF-7 cells from cisplatin-induced apoptosis, which is mediated by activating STAT3 signaling pathway with the markedly decreasing expression of Bax." (PMID 34095111, 2021). "Previous studies suggested that Jak2 induction of Jak2 activity upstream of STAT3 in breast cancer cells is a crucial step for the estrogen (ER)-dependent progression of cancer." (PMID 34833950, 2021). "Intercellular STAT3 activation of immune cells plays a central role in breast cancer TME immunosuppression and distant metastasis." (PMID 33957948, 2021). "Docetaxel polarizes MDSCs toward M1-like phenotype and upregulates macrophages markers (CD86, MHC class II, and CD11c) in vivo and in vitro partly through an inhibition of STAT-3 in 4T1-Neu mammary cancer implants." (PMID 34283088, 2021). "We further demonstrated that STAT3 cooperates with SHOX2 to form a functional immunocomplex on the WASF3 promoter to promote WASF3 transcriptional activity in breast cancer cells." (PMID 34465361, 2021).
breast cancer (continued). "In breast cancer, applying the niclosamide to block the STAT3 overcame the radioresistance and significant increase of radiation-induced ROS, which offers an effective alternative approach for improving the breast cancer radiation therapy." (PMID 33957948, 2021). "In breast cancer, however, the partial functional loss of TFEB by the interaction of signal transducer and activator of transcription 3 (STAT3) enhances lysosomal-mediated cell death, thus serving as an anticancer action." (PMID 34490237, 2021). "Our previous studies have shown that CSE/H2S system can promote process and metastasis of breast cancer via the STAT3 signaling pathway and VEGF signaling pathway." (PMID 33903672, 2021). "Blocking of STAT3 in breast cancer not only suppressed the tumor progression, but also conferred sensitivity to chemotherapeutic drugs." (PMID 33957948, 2021). "In the present study, we investigated the inhibitory effect of E2 on heteronemin-induced cytotoxic effects via suppressing activation of ERK1/2 and STAT3 in breast cancer cells." (PMID 34381775, 2021). "In conclusion, we discovered that circRHOT1 contributed to malignant progression and attenuated ferroptosis in breast cancer by the miR-106a-5p/STAT3 axis." (PMID 33686957, 2021). "Scholars discovered the GPX8/IL-6/STAT3 axis as an essential pathway in regulating cell aggressiveness of breast cancer." (PMID 34284774, 2021). "Next, we further investigated the role of circRHOT1/miR-106a-5p/STAT3 axis in the modulation of breast cancer progression." (PMID 33686957, 2021). "In the present study, we evaluated the activities of a novel Stat3 inhibitor named Statmp-151 in the human breast cancer cell lines MCF-7 and MDA-MB-231 and the murine mammary carcinoma cell line 4T1." (PMID 33967793, 2021). "STAT3 is constitutively activated in all subtypes of breast cancers and particularly plays an essential role in their immunosuppression." (PMID 33957948, 2021). "Circular RNA RHOT1 promoted metastasis and suppressed ferroptosis via the miR-106a-5p/STAT3 axis in breast cancer." (PMID 34413915, 2021). "API has shown growth inhibitory properties in breast cancer via apoptosis promotion via blocking STAT3 signaling in breast cancer cells with HER2-overexpression." (PMID 34829751, 2021). "APG inhibited the expression of HIF-1α and mediated cell death through the suppression of STAT3 under hypoxia in breast cancer cells, suggesting that APG is a powerful anti-cancer drug to overcome hypoxia-induced chemoresistance." (PMID 34948250, 2021). "Synergistic effects showing a decrease from 20 to 17 hours in cell death time was observed in all human breast cancer cell lines when a selective STAT3 inhibitor was combined to CT." (PMID 33544704, 2021). "Specifically, elevated Foxp3 gene expression and accumulated Foxp3+ Tregs amount were detected in close proximity to lung metastases of breast cancer, as well as higher STAT3 activities." (PMID 33957948, 2021). "Taken together, these data suggest that circRHOT1 contributes to breast cancer progression by miR-106a-5p/STAT3 axis." (PMID 33686957, 2021). "Studies reported that upregulation of the JAK‐STAT signaling pathway and inhibition of STAT3 decrease the stem cell population in breast cancer." (PMID 33634982, 2021). "Together, our findings shed new light into the pathobiology of breast cancer with concurrent expression of TrkA and STAT3." (PMID 34066153, 2021). "MiR-365a-3p targeted STAT3 in breast cancer cells and circNOLC1 enhanced STAT3 expression by sponging miR-365a-3p." (PMID 34789263, 2021). "Further corroborating these observations, the inhibition of both FAK and STAT3 strongly reduced mammosphere formation, migration and invasion of breast cancer cells." (PMID 33562737, 2021). "Inactivation of STAT3 contributed to breast cancer immunogenic phenotype, which involved the participation of CD4+ T cells and NKs, and decreased Tregs in the TME." (PMID 33957948, 2021).
breast cancer (continued). "In conclusion, our study demonstrated that EZH2 non-canonically methylated and promoted the nuclear localization of pivotal transcriptional factor STAT3 in breast cancer." (PMID 34335938, 2021). "A considerable amount of literature from clinical and preclinical studies has extensively revealed the aberrant overactivity of the STAT3 pathway, which plays a vital role in breast cancer progression and development." (PMID 34298639, 2021). "The bioactivity was confirmed by induction of OSM/OSM receptor signaling through STAT3 phosphorylation in human breast cancer cells." (PMID 34376712, 2021). "STAT3 positively has been shown to positively regulate the expression of TGF-β1 in breast cancer, thereby promoting cancer cell proliferation and metastasis." (PMID 33957948, 2021). "In this study, primaquine, a malaria drug, was found to induce early endosome damage and reduce nEGFR; primaquine was also found to induce apoptosis levels in breast cancer through nEGFR/Stat3-dependent c-Myc downregulation." (PMID 34884765, 2021). "Related to its inhibitory activity against JAK, indirubin-induced apoptosis has been related to STAT3 inhibition, as seen in breast cancer, prostate cancer and melanoma cells." (PMID 34679649, 2021). "In 2018, Huang and colleagues reported that Src activates STAT3 and forms an Src-STAT3 enhanceosome in the nucleus for inducing gene regulation and the proliferation of breast cancer cells." (PMID 33794926, 2021). "Some researchers have proposed that DHTS inhibits breast cancer stem cells through the STAT3 signaling pathway." (PMID 33995073, 2021). "The direct antitumor effect of STAT3 inhibitors alone has been established in several pre- clinical breast cancer studies." (PMID 33957948, 2021). "On the one hand, knockdown of SMARCAD1 resulted in a significant decrease in breast cancer cell proliferation and colony formation, mainly through a potent inhibition of STAT3 phosphorylation." (PMID 34315468, 2021). "As is the case for NFκB, the activation of STAT3 in breast cancer promotes the transcription of Lin28B by directly binding to the Lin28B promoter, resulting in the repression of let-7 expression and concomitant upregulation of the let-7 target, HMGA2." (PMID 34572067, 2021). "STAT3 is a component of another important pathway that plays a role in inflammation during breast cancer progression, and several lncRNAs (e.g., HOTAIR and Lnc-BM) participate in this process." (PMID 34123857, 2021). "For example, lnc-BM promotes the JAK2/STAT3 pathway to facilitate brain metastasis in breast cancer." (PMID 34765550, 2021). "For example, miR-148a has been documented to function as a tumor suppressor in pancreatic cancer, gastric cancer, and breast cancer through targeting ErbB3, STAT3, and CCK-BR, respectively." (PMID 34836544, 2021). "STAT3 is persistently activated in human malignancies including liver cancer, breast cancer, prostate cancer, ovarian cancer, kidney cancer, and head and neck cancer." (PMID 35053027, 2021). "Yu and coworkers also reported that CD11b + myeloid precursor cells derived from bone marrow were stimulated by exosomes from murine mammary tumor cells and upregulated STAT3." (PMID 33509150, 2021). "Eventually, disturbed STAT3 methylation by EZH2 in animal model showed decreased breast cancer growth." (PMID 34335938, 2021). "For instance, it was found to exert doxorubicin resistance in breast cancer cells by blocking the chemotherapy-induced apoptosis via activating STAT3 signaling." (PMID 34588926, 2021). "Apigenin reduces p-JAK1/2 and p-STAT3 in breast cancer (BT-474) cells, and demonstrates anticancer activity by inhibiting JAK-STAT." (PMID 34539403, 2021). "In relation to obesity, the adipokine leptin can induce cell migration and invasion of breast cancer cells in a FAK-Src-STAT3 dependent manner." (PMID 33738261, 2021).
breast cancer (continued). "Upregulated and phosphorylated STAT1 and STAT3 are known to promote breast cancer progression and drug resistance and high levels are associated with poor outcomes and shorter survival in a variety of cancers." (PMID 34944900, 2021). "Ongoing phase I trial (NCT03195699) in advanced-stage breast cancer patients applied the STAT3 SH2-domain binder inhibitor C188-9." (PMID 33957948, 2021). "Recent findings demonstrated that, through phosphorylation of STAT3, syntenin-1 increases the expression of PD-L1 in both breast cancer cell lines and in tumor tissues derived from patients with TNBC cocultured with T CD8+ cells." (PMID 33506060, 2021). "In this review, we summarize the available information on the functions of STAT3-related immune cells in TME of breast cancer, as well as the specific upstream and downstream targets." (PMID 33957948, 2021). "Here, we reported for the first time that EZH2 exacerbates breast cancer by directly methylating and activating STAT3." (PMID 34335938, 2021). "In breast cancer, phosphorylated-STAT3 directly induced indoleamine 2,3-dioxygenase (IDO) expression in MDSCs by binding to the promotor of IDO which is involved in immunosuppressive effects between breast cancer-derived MDSCs on T cells." (PMID 33957948, 2021). "In summary, our findings indicate that CCL16 expression is up-regulated by IL10/STAT3 signaling in breast cancer in vitro and in vivo." (PMID 33500726, 2021). "Pimozide also acts as a STAT5 inhibitor or STAT3 inhibitor to kill breast cancer cells or sensitize cancer cells to other drugs." (PMID 34336684, 2021). "miR-124 was negatively regulated in HER2-positive breast cancer cells; this miRNA directly targets STAT3, which regulates HER2 expression." (PMID 34804940, 2021). "This review focuses on roles of miRNAs in breast cancer progression, particularly their involvement in Wnt/β-catenin, Notch, PI3K/AKT/mTOR, BMI-1 and STAT3 pathways in breast cancer stem cells (BCSCs)." (PMID 33413418, 2021). "In fact, immunohistocheical staining showed that STAT3 was highly expressed in patients tissue and predminantly located within nuclei which indicated its high activity in breast cancer." (PMID 34335938, 2021). "Not surprisingly, OSM has also been shown to induce EMP by regulating the Lin28/Let7/HMGA2 and miR200/Zeb1 circuits via STAT3 in breast cancer, leading to the initiation and maintenance of an EMP program both in vitro and in vivo." (PMID 34361105, 2021). "STAT3 helix 2 analogs were rationally designed and demonstrated the potential to induce apoptosis of breast cancer cells." (PMID 33382511, 2021). "HIF-1α induces PKM2 expression, which maintains STAT3 tyrosine phosphorylation, a mechanism that initiates a positive feedback loop that leads breast cancer cells to adapt and grow into hypoxia conditions." (PMID 33718197, 2021). "Signal transducer and activator of transcription 3 (STAT3) is a transcriptional factor ectopically expressed in various cancer types including breast cancer." (PMID 34335938, 2021). "In breast cancer cells, Lnc-BM increased the STAT3-dependent expression of ICAM1 and CCL2, which regulated vascular co-option and recruitment of macrophages in the brain, respectively." (PMID 34123857, 2021). "A positive and direct correlation between the activation of STAT3 and the increased expression of PD-L1 in breast cancer cells has been established in both human cell lines and breast cancer samples, being stronger in TNBC specimens." (PMID 33506060, 2021). "Our data showed that primaquine downregulated the c-Myc gene through the regulation of the nEGFR/Stat3 complex and induced the apoptosis of breast cancer cells." (PMID 34884765, 2021). "We then assessed the function of miR-365a-3p/STAT3 axis in the regulation of breast cancer functions." (PMID 34789263, 2021).
breast cancer (continued). "Liposomal nanoparticles (NPTs) containing hydrazinocurcumin, a synthetic analog of curcumin, were used to suppress STAT3 activity in M2-like TAMs in a breast cancer model, re-educating TAM to M1 phenotype and restoring the crosstalk with tumor cells." (PMID 33572626, 2021). "In summary, Statmp-151 is a small molecule compound that was confirmed to inhibit the growth of breast cancer cells in vitro and in vivo by blocking Stat3 activation in this study." (PMID 33967793, 2021). "The operation of TPH1-5-HT-5-HT7 axis utilized PI3K/Akt and JAK2/STAT3 signaling pathways that were activated through Gβγ components of the receptor, consistent with our previous findings in breast cancer cells." (PMID 34771469, 2021). "In one study, 3/7 equine mammary carcinomas exhibited nuclear STAT3 expression, implying transcriptional activation of STAT3." (PMID 33280071, 2021). "It has been proven that cells expressing STAT3, with a mitochondrial localization sequence, exhibit enhanced tumor growth and complex I activity in breast cancer cells." (PMID 33003453, 2020). "In conclusion, our data suggest that PA can act as an effective apoptotic compound in human and mouse metastatic breast cancer cells through the inhibition of Akt, STAT3, and p38 MAPK and activation of the ER stress response." (PMID 33182770, 2020). "Conversely, the STAT3 and NF-κB pathways can be disrupted upon Syndecan ablation in breast cancer via Notch signaling." (PMID 33333886, 2020). "Tofacitinib treatment of breast cancer cells prevented activation and nuclear localization of STAT3." (PMID 33521321, 2020). "A study has reported substantial correlation between the occurrence of polyphenols and in vivo tumor growth inhibition via regulating MAPK/ERK, PI3K/AKT and STAT3 pathways in lung metastasis and breast cancer stem cells." (PMID 32552791, 2020). "LncRNA H19 inhibits the down-regulation of miR-93 to enhance the expression of STAT3 signaling pathway leading to the increased proliferation and metastasis of breast cancer cells." (PMID 32612456, 2020). "STAT3 (Signal transducer and activator of transcription 3) protein is a constitutive transcription factor expressed in several human tumors such as multiple myeloma, leukemia, lymphoma, breast cancer, prostate cancer, squamous cell carcinoma of head and neck." (PMID 32283655, 2020). "It showed anticancer activity via JAK/STAT pathway inhibition by reducing phosphorylated JAK1/2 and STAT3 in breast cancer (BT-474) cells." (PMID 32545187, 2020). "Recruited macrophages in turn produced oncostatin M and IL-6, and then activated the Lnc-BM/JAK2/STAT3 pathway to promote breast cancer brain metastases." (PMID 32929060, 2020). "IL-22 increased phosphorylated STAT3 level and proliferation of breast cancer cells in vitro, an effect blocked by a STAT3-inhibitor stattic." (PMID 32649314, 2020). "The addition of cryptotanshinone, a well-characterized inhibitor of STAT3, to the cells treated by sclareol enhanced the inhibitory effect of sclareol and confirmed that the effects of sclareol on breast cancer cells are mediated through JAK/STAT pathway." (PMID 32922496, 2020). "Stimulation of breast cancer cells with resistin not only enhances their growth and stemness but also results in chemoresistance through STAT3 activation." (PMID 33123472, 2020). "STAT3 is in general transiently activated in normal cells but constitutively activated in a variety of solid tumors, including breast cancer, prostate cancer, head and neck cancer and GC cancers 35-38." (PMID 31949488, 2020). "Constitutively activated STAT3 has been observed in various cancers and shown to enhance cell proliferation, invasion, and survival and to inhibit apoptosis in breast cancer cells." (PMID 32340377, 2020). "Taken together, these findings propose a novel mechanism responsible for NF-κB activation by STAT3 through stabilization of IKKα, which contributes to breast cancer promotion and progression." (PMID 33396715, 2020).